RNU4-82P (RNA, U4 small nuclear 82, pseudogene)
Gene: Small nuclear RNA gene on chromosome 9 (124,887,410 to 124,887,549, reverse strand). Ensembl gene ENSG00000199313.
Homologues: Orthologues: macaque U4 (91% identical), macaque U4 (73% identical), chimpanzee U4 (66% identical), guinea pig U4 (55% identical), rat LOC120096861 (53% identical). Paralogues in human: RNU4-22P (59% identical), RNU4-39P (57% identical), RNU4-4P (57% identical), RNU4-48P (56% identical), RNU4-55P (56% identical), RNU4-74P (56% identical), RNU4-91P (56% identical), U4 (56% identical), RNU4-57P (55% identical), RNU4-6P (55% identical), RNU4-9P (55% identical), RNU4-5P (54% identical), and 82 more.